CACNA2D1 (calcium voltage-gated channel auxiliary subunit alpha2delta 1)
Description:
The alpha-2/delta subunit of voltage-dependent calcium channels regulates calcium current density and activation/inactivation kinetics of the calcium channel. Plays an important role in excitation-contraction coupling (By similarity).
Synonyms: CACNL2A; CCHL2A; lncRNA-N3; alpha2delta-1; CACNA2; DEE110; LINC01112; formerly MHS3
Tractability: Small molecule: an approved drug acts on it; a structure with a bound ligand is known; a high-quality ligand is known; it belongs to a druggable protein family. Antibody: UniProt places it where antibodies can reach, with high confidence; its Gene Ontology location is reachable by antibodies, with high confidence; UniProt predicts a signal peptide or a membrane-spanning region. PROTAC: its protein half-life has been measured; a small molecule that binds it is known.
Target class: Auxiliary transport protein; Calcium channel auxiliary subunit alpha2delta family
Gene: Protein-coding gene on chromosome 7 (81,946,444 to 82,443,970, reverse strand). Ensembl gene ENSG00000153956.
Subcellular location: Membrane; Cell membrane
Pathways (Reactome):
Cellular responses to stimuli: Mechanical load activates signaling by PIEZO1 and integrins in osteocytes
Gene Ontology:
Molecular function: voltage-gated calcium channel activity; voltage-gated calcium channel activity involved in bundle of His cell action potential; voltage-gated calcium channel activity involved in cardiac muscle cell action potential
Biological process: calcium ion transport; cardiac muscle cell action potential involved in contraction; cellular response to amyloid-beta; membrane depolarization during bundle of His cell action potential; regulation of calcium ion transmembrane transport via high voltage-gated calcium channel; regulation of calcium ion transport; regulation of heart rate by cardiac conduction; regulation of ventricular cardiac muscle cell membrane repolarization; calcium ion import across plasma membrane; calcium ion transmembrane transport via high voltage-gated calcium channel; calcium ion transport into cytosol; regulation of membrane repolarization during action potential; positive regulation of insulin secretion involved in cellular response to glucose stimulus
Cellular component: extracellular exosome; L-type voltage-gated calcium channel complex; plasma membrane; voltage-gated calcium channel complex; GABA-ergic synapse; membrane; neuronal dense core vesicle; presynaptic active zone membrane; sarcoplasmic reticulum; T-tubule
Genetic constraint (gnomAD): Loss-of-function variants: 17 observed, 58.29 expected, observed/expected ratio (o/e) 0.29, 90% interval 0.2 to 0.44. The upper end of that interval is the gene's LOEUF score, 0.44, which puts it in group 1 of 6, group 1 being the genes least tolerant of losing a copy. Missense variants: 394 observed, 545.67 expected, observed/expected ratio (o/e) 0.72, 90% interval 0.66 to 0.79. Synonymous variants: 203 observed, 191.75 expected, observed/expected ratio (o/e) 1.06, 90% interval 0.94 to 1.19.
Gene-disease validity (ClinGen):
ClinGen rates the evidence that CACNA2D1 causes each of these diseases.
Brugada syndrome 1 (autosomal dominant): Disputed. Any Brugada syndrome in which the cause of the disease is a mutation in the SCN5A gene.
short QT syndrome (autosomal dominant): Disputed.
Homologues: Orthologues: chimpanzee CACNA2D1 (99% identical), macaque CACNA2D1 (99% identical), dog CACNA2D1 (96% identical), mouse Cacna2d1 (96% identical), rat Cacna2d1 (96% identical), pig CACNA2D1 (95% identical), guinea pig CACNA2D1 (93% identical), rabbit CACNA2D1 (88% identical), tropical clawed frog cacna2d1 (77% identical), zebrafish CACNA2D1 (63% identical), zebrafish cacna2d1a (62% identical), Drosophila melanogaster stj (25% identical), and 1 more. Paralogues in human: CACNA2D2 (53% identical), CACNA2D3 (29% identical), CACNA2D4 (29% identical), CACHD1 (20% identical).
Diseases named in the same sentence as CACNA2D1 in open-access papers:
CACNA2D1 is named in the same sentence as 81 diseases in open-access papers, as found by Europe PMC text mining. Sharing a sentence is not in itself a finding about the gene and the disease. The quoted sentences say what the papers report.
epilepsy (17 papers, 2017 to 2023). A brain disorder characterized by episodes of abnormally increased neuronal discharge resulting in transient episodes of sensory or motor neurological dysfunction, or psychic dysfunction. "CACNA2D1 encodes a protein in the voltage-dependent calcium channel complex, which is essential in neurotransmission, and is associated with epilepsy, intellectual disability, and cardiac arrhythmias which are conditions with an increased prevalence in 45,X." (PMID 36978128, 2023). "Disruptions in the CACNA2D1 gene have been linked to epilepsy and intellectual disability in a few individuals." (PMID 33653397, 2021). "Calcium voltage-gated channels are important for neurotransmission, and genomic aberrations of the CACNA2D1 gene have been linked to autism spectrum disorder, epilepsy, and neuropsychiatric disorders." (PMID 33441551, 2021). "Exome sequencing has identified various mutations of CACNA1D in ASD, epilepsy developmental delay endocrine issues, CACNA2D1 in epilepsy and intellectual disability and CACNB2 mutations in ASD." (PMID 33338084, 2020). "Over the past years, various genetic studies implied CACNA2D1, the gene encoding the α2δ-1 isoform, in various forms of epilepsy and psychiatric disorders including major depressive disorders (MDDs), BPD, and SCZ (CADNA2D1)." (PMID 32607809, 2020). "There were 3 VUS inherited from asymptomatic parents intersecting with genes within CNVs that have previously been implicated with disorders, such as CACNA2D1 with epilepsy and ID, and MACROD2 and LINGO2 with autism." (PMID 29441128, 2018). "α2δ-1 (encoded by the Cacna2d1 gene), previously known as a subunit of voltage-gated calcium channels, is a binding protein of gabapentinoids used clinically for treating chronic neuropathic pain and epilepsy." (PMID 37153659, 2023). "Similarly, the role of heterozygous variants in CACNA2D1 as a predisposing factor to epilepsy and/or intellectual disability remains to be confirmed." (PMID 37047073, 2023). "Recently, the human genes (CACNA2D1–4) encoding for the four known α2δ proteins (isoforms α2δ-1 to α2δ-4) have been linked to a large variety of neurological and neuropsychiatric disorders including epilepsy, autism spectrum disorders, bipolar disorders, schizophrenia, and depressive disorders." (PMID 32607809, 2020). "Our review has further revealed variants in CACNA1C, CACNA1F, CACNA1I, CACNA2D1 and CACNA2D2 as additional genes related to epilepsy." (PMID 33985586, 2021). "A genomic aberration affecting the CACNA2D1 gene has been previously characterized in patients with epilepsy and ID, pinpointing the gene as an interesting candidate gene for these clinical features." (PMID 34356170, 2021). "Our data provide support for the reported association of CACNA2D1 and CACNA2D3 genetic aberrations with autism and the high comorbidity of epilepsy in individuals with autism." (PMID 32414783, 2020). "Four patients with RE carried CNVs that disrupted genes known to cause other epilepsies; KCTD7, ARHGEF4, ARHGEF15 and CACNA2D1, expanding the phenotypes associated with these genes." (PMID 29789371, 2018). "CACNA2D1 and CACNA2D2 are both associated with epilepsy and ID, while CACN2D3 has been recently implicated in ASD." (PMID 28713243, 2017). "Importantly, chromosomal deletions affecting CACNA2D1 were identified in three patients with epilepsy and intellectual disability." (PMID 32607809, 2020). "Five patients with RE carried a rare CNV that disrupted genes associated with other epilepsies (KCTD7, ARHGEF15, CACNA2D1, GRIN2A and ARHGEF4), and 17 cases carried CNVs that disrupted genes associated with other neurological conditions or that are involved in neuronal signalling/development." (PMID 29789371, 2018).
epilepsy (continued). "Using qRT–PCR, we validated the downregulation of ASD-related genes involved in cerebellar development (Cadps2 and Reln) (refs 28, 43), and ASD- or epilepsy-related ion channels in neurons (Cacna2d1, Grik2 and Kcnd2) (refs 43, 44, 45) in ICRF-193 treated or Chd7 mutant CGNs." (PMID 28317875, 2017). "There is also support for CACNA2D1 in other psychiatric disorders that are correlated with SCZ, e.g., epilepsy and intellectual disability, and CACNA2D1 has been identified as a potential drug target in MDD from GWAS." (PMID 35205424, 2022). "Our review has highlighted CACNA1C, CACNA1F, CACNA1I, CACNA2D1 and CACNA2D2 as additional genes for epilepsy, and CACNA2D1 for autism spectrum disorder." (PMID 33985586, 2021).
mastitis (8 papers, 2017 to 2025). Inflammation of breast tissue during lactation or postpartum due to an obstructed duct or infection. "Moreover, investigations have unveiled that certain polymorphisms (G519663A and G38819398A) within the Calcium channel, voltage-dependent, alpha-2/delta subunit 1 (CACNA2D1) gene are associated with mastitis resistance in Sahiwal cattle." (PMID 38259482, 2023). "Calcium voltage-gated channel auxiliary subunit alpha 2 delta 1 (CACNA2D1), which is a member of the calcium voltage-gated channel auxiliary subunit alpha-2/delta, has been previously reported to be a candidate gene associated with somatic cell score and mastitis resistance." (PMID 36611624, 2022). "These included genes and QTLs related to somatic cell count and mastitis (CACNA2D1, SEMA5A, NEGR1, PTK2B, CTNNA3), gastrointestinal parasites (PTK2B), and various viral or bacterial diseases." (PMID 41273432, 2025). "Proteins like complement C4 (C4), BRCA1, TLR4, MBLA, and calcium voltage-gated channel auxiliary subunit alpha2delta 1 (CACNA2D1) are reported potential biomarkers in mastitis which were also found in our study." (PMID 34222390, 2021). "Moreover, proteins like complement C4 (C4), BRCA1, TLR4, MBLA, and calcium voltage-gated channel auxiliary subunit alpha2delta 1 (CACNA2D1) have been found during mastitis in buffalo and are also reported as potential biomarkers in livestock mastitis." (PMID 39858163, 2025).
autism (7 papers, 2015 to 2024). Persistent deficits in social interaction and communication and interaction as well as a markedly restricted repertoire of activity and interest as well as repetitive patterns of behavior. "Several potential autism-causing mutations in the coding sequence of CACNA2D1 and CACNA2D3 have been identified in patients with ASD." (PMID 39770450, 2024). "CACNA2D1 regulates influx of calcium ions into the cell upon membrane polarization and Mutations in a related gene (CACNA1C) are known to cause Timothy syndrome which includes neurological and developmental deficits and often autism symptoms." (PMID 26185613, 2015). "Furthermore, both CACNA2D1 and CACNA2D3 genes are included in the Simons Foundation Autism Research Initiative (SFARI) gene list, which serves as an extensive database that includes all genes associated with autism risk." (PMID 39770450, 2024).
Brugada syndrome (7 papers, 2017 to 2025). A genetically heterogeneous condition characterized by complete or incomplete right bundle branch block accompanied by ST elevation in leads V1-V3. "Loss of function mutations of CaV1.2 or CACNA2D1, such as Brugada syndrome, can lead to a reduction in Ca2+ currents and short QT intervals, which increases the risk for arrhythmias and sudden cardiac death." (PMID 36902065, 2023). "CACNA2D1 is associated with Brugada syndrome, also known as sudden unexpected nocturnal death syndrome, a heart condition that causes ventricular arrhythmia." (PMID 29257745, 2017). "In contrast, rare variants located in genes encoding calcium (CACNA1C, CACNA2D1, and CACNB2) and the SCN5A gene, have been associated with Brugada syndrome (BrS) concomitant with shortened QT intervals, but without a conclusive diagnosis of SQTS." (PMID 30420954, 2018).
autism spectrum disorder (4 papers, 2020 to 2024). A spectrum of developmental disorders that includes autism, and Asperger syndrome. "Several rare missense variants in CACNA2D1 (coding for α2δ-1) and CACNA2D3 (coding for α2δ-3) genes were identified in patients with autism spectrum disorder (ASD)." (PMID 39770450, 2024). "Besides, CACNA2D1 is related to autism spectrum disorder while CACNA1A, CACNA1C and CACNA2D1 are candidate genes for attention deficit hyperactive disorder." (PMID 33985586, 2021).
cardiomyopathy (4 papers, 2019 to 2025). A disease of the heart muscle or myocardium proper. "CACNA2D1 has been found to be involved in cardiomyopathy pathway." (PMID 31888606, 2019).
gastric cancer (4 papers, 2022 to 2025). A primary or metastatic malignant neoplasm involving the stomach. "A high expression of CACNA2D1 was associated with a poor prognosis in several cancers, including ovarian cancer, lung cancer, hepatocellular cancer and gastric cancer." (PMID 36231119, 2022). "CACNA2D1 is involved in voltage-gated calcium channel activity and regulates tumour growth via the apoptosis signalling pathway in gastric cancer." (PMID 40429844, 2025). "CACNA2D1 has been reported to have potential as a therapeutic target for gastric cancer, lung cancer and epithelial ovarian cancer." (PMID 36231119, 2022).
glaucoma (4 papers, 2017 to 2022). Increased pressure in the eyeball due to obstruction of the outflow of aqueous humor. "Using human genome-wide association study (GWAS) data, evidence for association of a CACNA2D1 single-nucleotide polymorphism and primary open angle glaucoma is found." (PMID 29176626, 2017). "Although they have inferior potency to PRG, both of the other compounds lower IOP, which in turn validates CACNA2D1 as a valuable drug target in treating glaucoma." (PMID 34577587, 2021). "Together, these data suggest CACNA2D1 is a validated drug target in treating glaucoma and worthy of further investigation for more potent compounds." (PMID 34577587, 2021). "In the current study, to further validate our target protein—CACNA2D1—as a potential target for the treatment of glaucoma, we used the docking method to identify several compounds that are structurally similar to PRG with a good affinity to the target protein." (PMID 34577587, 2021). "Collectively, our data identify CACNA2D1 as a modulator of IOP and provide an avenue for a precision medicine approach to glaucoma therapy." (PMID 29176626, 2017).
short QT syndrome (3 papers, 2018 to 2021). A genetic disease of the electrical system of the heart that consists of a constellation of signs and symptoms, consisting of a short QT interval on an EKG (< 300 ms) that does not significantly change with heart rate, tall and peaked T waves, and a structurally normal heart. "It has been reported that mutations in CACNA2D1 cause a variant of short QT syndrome, which is associated with sudden cardiac death in humans." (PMID 32344918, 2020). "Mutations in the regulatory Cacna2d1 are also associated with cardiac deficiencies, including Brugada and short QT syndromes." (PMID 30400228, 2018).
Ataxia (2 papers, 2021 to 2024). Ataxia refers to impaired coordination of voluntary muscle movement. "There are several reports that the defect in CACNA2D1 or CACNA2D2 causes developmental and epileptic encephalopathies, hypotonia, and severe cerebellar ataxia, symptoms of which can be also observed in IGDs, including PIGA deficiencies." (PMID 38225934, 2024).
Azoospermia (2 papers, 2019 to 2022). Absence of any measurable level of sperm,whereby spermatozoa cannot be observed even after centrifugation of the semen pellet. "It was demonstrated that two disrupted genes, DPP6 and CACNA2D1, were at breakpoint sites of the chromosomes, suggesting they may be associated with azoospermia." (PMID 31231514, 2019). "Taken together, it can be suggested that the aberration or disruption of CACNA2D1 can be a biomarker for azoospermia." (PMID 35173218, 2022).
breast carcinoma (2 papers, 2022). "In addition, CACNA2D1 was identified as a surface marker of cancer stem cells in liver cancer and breast cancer." (PMID 36231119, 2022).
chronic myeloid leukaemia (2 papers, 2020 to 2022). "CACNA2D1 downregulation was reported to induce the erythroid differentiation of chronic myeloid leukemia cells, indicating that CACNA2D1 might be associated with higher cell stemness." (PMID 36231119, 2022). "PE‐Ima (LIF, MRGPRF, GRM3, TNNI1 and CACNA2D1) predicted imatinib response in chronic myelogenous leukaemia patients." (PMID 34766125, 2020). "Downregulation of CACNA2D1 from PE‐Ima is associated with erythroid differentiation of K562 and KCL‐22 chronic myeloid leukaemia cells." (PMID 34766125, 2020).
developmental delay (2 papers, 2020 to 2022). "In conclusion, our data demonstrate that biallelic loss-of-function variants in CACNA2D1 underlie early-onset DEE characterized by microcephaly, profound developmental delay, seizures, visual impairment, truncal hypotonia, limb spasticity and movement disorder." (PMID 35293990, 2022).
endometrial carcinoma (2 papers, 2022 to 2025). A malignant tumor arising from the epithelium that lines the cavity of the uterine body. "Furthermore, inhibiting CACNA2D1 has been shown to suppress cell proliferation and migration in endometrial cancer." (PMID 40429844, 2025). "First, endogenous CACNA2D1 expression was examined by Western blotting in eight endometrial carcinoma cell lines, among which the HEC-108, KLE, Ishikawa and HEC-06 cell lines showed relatively higher levels of CACNA2D1 than the other four EC cell lines." (PMID 36231119, 2022).
epileptic encephalopathies (2 papers, 2022 to 2024). "Here we report biallelic variants in CACNA2D1, encoding the α2δ-1 protein, in two unrelated individuals showing a developmental and epileptic encephalopathy." (PMID 35293990, 2022).
head and neck squamous cell carcinoma (2 papers, 2020 to 2025). A squamous cell carcinoma that arises from any of the following anatomic sites: lip and oral cavity, nasal cavity, paranasal sinuses, pharynx, larynx, and salivary glands. "Our replication study yielded two SNPs, TMC6/TMC8:rs9893818 which was reported to be associated with CIN3/cervical cancer and CACNA2D1:rs2299187, which was associated with survival of head and neck squamous cell carcinoma in a recent GWAS." (PMID 33225922, 2020). "Elevated expression of CACNA2D1 has been observed in head and neck squamous cell carcinoma tissue but not in normal tissue, and a high expression of CACNA2D1 has been associated with a poor prognosis in patients with gastric, breast, and epithelial ovarian cancers." (PMID 40429844, 2025).
Hypertension (2 papers, 2025). The presence of chronic increased pressure in the systemic arterial system. "Exercise-induced downregulation of CACNA2D1 and a decrease in Ca2+ concentration both diastolized vascular smooth muscle and attenuated the cardiac damage caused by hypertension in mice." (PMID 40596125, 2025).
nasopharyngeal carcinoma (2 papers, 2025). A carcinoma arising from the nasopharyngeal epithelium. "In this study, we leveraged an AI-driven drug target screening platform, PandaOmics, to identify CACNA2D1 as a potential oncogenic agent activated by enhancer infestation in Epstein–Barr virus-associated nasopharyngeal carcinoma (NPC)." (PMID 40429844, 2025). "Genetic depletion of CACNA2D1 in EBV+ nasopharyngeal cancer cell line evidently reduced its proliferation in vitro and in vivo." (PMID 41402855, 2025). "Via exploiting PandaOmics, Chueng and colleagues pinpointed that voltage-dependent calcium channel subunit alpha-2/delta-1 (CACNA2D1) might act as a potential therapeutic target in Epstein-Barr virus positive (EBV+) nasopharyngeal cancer." (PMID 41402855, 2025). "Indeed, nasopharyngeal cancer expressed higher CACNA2D1 transcript and protein levels compared to normal nasopharyngeal samples." (PMID 41402855, 2025).